AOX2P (aldehyde oxidase 2, pseudogene)
Synonyms: AOH2; AOX2; AOX3L1
Gene: Transcribed unprocessed pseudogene on chromosome 2 (200,738,608 to 200,791,630, forward strand). Ensembl gene ENSG00000243478.
Diseases named in the same sentence as AOX2P in open-access papers:
AOX2P is named in the same sentence as 1 disease in open-access papers, as found by Europe PMC text mining. Sharing a sentence is not in itself a finding about the gene and the disease.
AOX2P shares sentences with these, for which no sentence is quoted: infection (2 papers).